ATOSB (atos homolog B)
Description:
Transcription regulator that may syncronize transcriptional and translational programs.
Synonyms: FAM214B; KIAA1539; FLJ11560; bA182N22.6
Tractability: No criterion of Open Targets' tractability assessment is met for any kind of drug.
Gene: Protein-coding gene on chromosome 9 (35,104,112 to 35,116,357, reverse strand). Ensembl gene ENSG00000005238.
Subcellular location: Nucleus
Subcellular location (Human Protein Atlas): Nucleoli fibrillar center; Nucleoplasm
Gene Ontology:
Molecular function: protein binding
Cellular component: nucleus
Genetic constraint (gnomAD): Loss-of-function variants: 15 observed, 38.19 expected, observed/expected ratio (o/e) 0.39, 90% interval 0.26 to 0.61. The upper end of that interval is the gene's LOEUF score, 0.61, which puts it in group 2 of 6, group 1 being the genes least tolerant of losing a copy. Missense variants: 624 observed, 666.45 expected, observed/expected ratio (o/e) 0.94, 90% interval 0.88 to 1. Synonymous variants: 265 observed, 269.47 expected, observed/expected ratio (o/e) 0.98, 90% interval 0.89 to 1.09.
Homologues: Orthologues: chimpanzee ATOSB (99% identical), macaque ATOSB (99% identical), rabbit ATOSB (94% identical), dog ATOSB (94% identical), pig ATOSB (93% identical), guinea pig ATOSB (92% identical), rat Atosb (92% identical), mouse Atosb (91% identical), tropical clawed frog atosb (45% identical), zebrafish atosb (41% identical). Paralogues in human: ATOSA (31% identical).
Diseases named in the same sentence as ATOSB in open-access papers:
ATOSB is named in the same sentence as 3 diseases in open-access papers, as found by Europe PMC text mining. Sharing a sentence is not in itself a finding about the gene and the disease.
ATOSB shares sentences with these, for which no sentence is quoted: prostate carcinoma (2 papers); benign prostatic hyperplasia (1); Prostate Tumor (1).